HAVCR2 (hepatitis A virus cellular receptor 2)
Diseases named in the same sentence as HAVCR2 in open-access papers (continued):
Sharing a sentence is not in itself a finding about the gene and the disease.
benign prostatic hyperplasia (1 paper, 2022). A non-cancerous nodular enlargement of the prostate gland. "The expression of T-cell immunoglobulin domain and mucin domain-containing molecule 3 (TIM-3) encoded by HAVCR2 in CD4+ and CD8+ T cells of the PCa patients was significantly increased compared with benign prostatic hyperplasia, suggesting that it may affect the development and progression of PCa." (PMID 35463369, 2022).
cervical disease (1 paper, 2021). "What stood out in the tables was the patients afflicted with the cervical disease showed positive correlation significantly, such as famous immune checkpoint genes (CTLA4, TIGIT, HAVCR2, LAG3, etc.)and costimulatory genes like ICOS, CD80, CD40, and so forth." (PMID 33694292, 2021).
emphysema (1 paper, 2024). "In this study, we examined HE-stained sections of lung tissue from wild-type and Havcr2 knockout (KO) mice following chronic tobacco exposure to elucidate the role of Tim3 in emphysema formation." (PMID 39555065, 2024). "Notably, the knockout of HAVCR2 further promotes the infiltration of CD4+ T cells and the expression of IFN-γ in the lungs, resulting in a more severe emphysema phenotype, although it does not significantly affect TNF-α expression." (PMID 39555065, 2024).
intraductal papillary mucinous neoplasms (1 paper, 2020). "The percentage of CD8A-positive T lymphocytes expressing HAVCR2 and/or PDCD1 was lower in cases of intraductal papillary mucinous neoplasms (IPMN) and serous cystadenoma (SC) compared to the percentage observed in PDAC." (PMID 32645996, 2020).
kidney tumors (1 paper, 2025). "On the other hand, higher methylation of PDCD1 and HAVCR2 was found in normal tissues compared to the respective tumors in BRCA, UCEC, kidney tumors, lung tumors, LIHC, and HNSC." (PMID 40076932, 2025).
leukoplakia (1 paper, 2024). A white patch or plaque on a mucous membrane that cannot be characterized clinically or pathologically as any other disease. "Finally, we found that NK/T cell subgroups in the HNSCC group highly expressed marker genes of depleted T cells such as CTLA4, LAG3, TIGIT, and HAVCR2, indicating that the inhibition degree of NK/T cells in the HNSCC group was stronger than that of leukoplakia." (PMID 38582791, 2024).
lung disease (1 paper, 2024). "Our findings revealed that the knockout of Havcr2 resulted in a further increase in CD4+ T cell expression in the lungs, indicating that Tim3 functions as an inhibitory factor for CD4 expression and that the absence of Havcr2 exacerbated lung disease associated with tobacco exposure." (PMID 39555065, 2024).
seminoma (1 paper, 2024). A radiosensitive malignant germ cell tumor found in the testis (especially undescended), and extragonadal sites (anterior mediastinum and pineal gland). "Furthermore, HAVCR2 expression levels were higher in seminoma patients compared with non-seminoma patients." (PMID 38791003, 2024).
tumor (2,574 papers, 2007 to 2026). "As LGALS9 and HAVCR2 genes are associated with immune regulation, we evaluated the correlation of these transcripts’ abundance with the gene signature of tumor microenvironment cells Cibersort ABS on TIMER®." (PMID 40666515, 2025). "HAVCR2 induces T cell exhaustion in cancer and chronic viral infections, and its expression in monocytes and tumor-associated macrophages is closely associated with higher HCC tumor grade and lower patient survival rates." (PMID 40821770, 2025). "We demonstrated that higher levels of sCD137 and sTIM3 were significantly associated with the risk of OS, and their corresponding genes TNFRSF9 and HAVCR2 were significantly elevated in tumor tissues." (PMID 38730580, 2024). "TIM-3, encoded by the HAVCR2 gene, has recently emerged as an immunotherapy target because it is co-expressed with PD-1 on dysfunctional and exhausted tumor-infiltrating T cells." (PMID 38791963, 2024). "T-cell exhaustion, characterized by increased PD1 and HAVCR2 expression, has also been previously linked to the tumor microenvironment." (PMID 39160510, 2024). "The patients in cluster 3 had the highest expression of PDL1 (encoding programmed cell death 1 ligand 11) and HAVCR2 (encoding Hepatitis A virus cellular receptor 2), and the highest tumor mutation burden (TMB)." (PMID 39184152, 2024). "The risk score was relevant with the tumor mutational burden and immune infiltration, and the expression of HAVCR2 was significant difference between 2 risk groups." (PMID 37986290, 2023). "Overexpression of HAVCR2 was associated with poor survival in tumor grades II, III, and IV and was the most correlated with immune infiltration of B and T cells." (PMID 35198632, 2022). "We further investigated the association of HAVCR2 expression and age, gender, and tumor node metastasis (TNM) stages." (PMID 36081997, 2022). "We further assessed diagnosis value, genetic alteration, epigenetic characteristics, correlation with tumor immunity, and signal pathways that are associated with the HAVCR2 gene." (PMID 36081997, 2022). "Those in the high-risk group express higher levels of PD-1, HAVCR2 and other immune checkpoint molecules to avoid the attack of anti-tumor immune cells." (PMID 34249015, 2021). "A higher CNV burden and attenuated anti-tumor immune activity, reflected by lower cytolytic activity scores, fewer neoantigens, and mRNA-level downregulation of immunomodulators such as HAVCR2 and LAG3, have been linked to early-onset OTSCC." (PMID 33923093, 2021). "Here we used Pdcd1 expression (which encodes for PD-1) as a surrogate marker of tumor specificity and observed that indeed, Pdcd1+ Havcr2– Slamf6+ cells were enriched in Tcf7+ cells compared to bulk Pdcd1+ or Pdcd1+ Havcr2– cells." (PMID 32174925, 2020). "Our results indicate a mechanism, underlying the roles of rs3087616 and rs4704846, in the regulation of TIM-3/HAVCR2 expression, and provide an explanation for the susceptibility to tumor formation associated with these SNPs." (PMID 29796301, 2018). "miRNAs can regulate the activity of TIM-3/HAVCR2, and dysregulation of miRNA is implicated in neoplasms." (PMID 29796301, 2018). "TIM-3 is a protein encoded by the HAVCR2 gene that mediates T-cell-mediated immune functions such as the response to tumor cells and cytotoxicity directed against tumor cell targets." (PMID 29867979, 2018). "Tim-3 (HAVCR2) is an emerging immune checkpoint receptor implicated in tumor immune evasion." (PMID 40666515, 2025). "In addition, blocking HAVCR2 and PD-1 caused tumor regression in preclinical models and boosted anti-tumor T cell responses in patients with advanced cancer." (PMID 37744335, 2023). "Finally, HAVCR2 can encode T‐cell immunoglobulin and mucin domain 3 (Tim‐3), a checkpoint receptor that plays vital roles within tumor microenvironment." (PMID 37178411, 2023).
tumor (continued). "Furthermore, the CD39 encoding gene ENTPD1 is among the most highly upregulated genes in CD8+ T cells isolated from tumor tissue, along with other T cell exhaustion marker encoding genes (HAVCR2, CTLA4, TIGIT)." (PMID 37648263, 2023). "Moreover, Eomes was co-expressed with Programmed Death-1 (PD-1, encoded by Pdcd1) and T-cell immunoglobulin and mucin-domain containing-3 (Tim-3, encoded by Havcr2) in CD8+ TILs by day 12 to day 25 of tumor challenge." (PMID 30619337, 2018). "Subsequently, low DNMT3A expression decreases methylation levels in HAVCR2 and LGALS9 promoters, promoting Tim-3 and Galectin-9 expression in HeLa and C-33A CC cells, suppressing the anti-tumor immunity mediated by innate and adaptive immune cells." (PMID 41226543, 2025). "The most prominent expression of HAVCR2 was observed in NK cells in all compartments followed by tumor-infiltrating lymphocytes, mainly CD8+ T cells and Tregs." (PMID 41323263, 2025). "After different levels of clustering, cell types of interest were identified, and the expression of LGALS9 and HAVCR2 was retrieved for each cell type and different compartments (blood, paratumor, and tumor tissue)." (PMID 41323263, 2025). "T-cell immunoglobulin mucin 3 (TIM-3), also known as HAVCR2, is a critical tumor immune checkpoint that was first identified in 2002,TIM-3 functions as a negatively regulated immune checkpoint." (PMID 40356928, 2025). "A hallmark of T cell exhaustion is the sustained expression of markers such as Tox, Ctla4, Entpd1, Pdcd1, and Havcr2, many of which were enriched in the tumor-infiltrating subset (Cluster 5)." (PMID 40229241, 2025). "This aligns with our broader analysis implicating chemokine ligands (CCL family), immune checkpoints (PD‐L1/CD274, PDCD1LG2, HAVCR2), and cell surface markers in shaping tumor immune phenotypes." (PMID 40693457, 2025). "Genes implicated in embryonic and organ development, including SHH, NEUROG3, and MAFA, were downregulated, while immune-related genes like CCL2 and HAVCR2 were upregulated, suggesting immune modulation and alterations within the tumour microenvironment." (PMID 40683913, 2025). "In light of these observations, it becomes evident that HAVCR2+ NK cells potentially contribute to tumor immune evasion." (PMID 39752457, 2025). "The expression of the LGALS9 gene is significantly upregulated in HRD tumor cells, which encodes a protein that is a ligand for HAVCR2/TIM3, a classical immunosuppressive molecule." (PMID 40830526, 2025). "HAVCR2 levels were also significantly higher on tumor samples (2.517 ± 0.19) than in normal tissue (1.188± 0.69)." (PMID 40666515, 2025). "Several inhibitory markers, including CD276, HAVCR2, CTLA4, PDCD1LG2, LAIR1, and ADORA2A, were significantly upregulated in the high-risk group (p < 0.05), suggesting an immunosuppressive tumor microenvironment." (PMID 40963600, 2025). "Exhaustion markers including PDCD1, IDO1, and HAVCR2 were predominantly enriched in tumor-adjacent regions, which exhibited partial spatial overlap with ADM expression." (PMID 40547013, 2025). "NK/T cell subgroups in HNSCC group highly expressed marker genes of depleted T cells such as CTLA4, LAG3, TIGIT, HAVCR2, etc., indicating that tumor tissue was more sensitive to NK/T cells." (PMID 38582791, 2024). "The findings demonstrated that cluster 1 has highly expressed immunosuppressive sites such as BTLA, CD200, CD200R1, CD44, HAVCR2, etc. that promote immunosuppression and tumor formation." (PMID 38347320, 2024). "Key immune checkpoints B7-H3 (CD276), OX40 (TNFRSF4) and TIM3 (HAVCR2) also displayed significantly higher expression (p < 0.05) in some tumor slides." (PMID 39529126, 2024). "A hallmark of T cells exhaustion is persistent expression of markers including Tox, Ctla4, Entpd1, Pdcd1, Havcr2, and others, many of which were expressed in the tumor TEX subset." (PMID 38496632, 2024).
tumor (continued). "Our results demonstrated that FGFBP2+ NK cells in tumor tissues exhibited a functionally inhibited state due to overexpression of HAVCR2." (PMID 38604154, 2024). "LGALS3 expression showed a significant positive association with CD274, TIGIT, PDCD1, HAVCR2, CTLA4, LAG3, as well as PDCD1LG2 after adjustment for tumor purity in HCC." (PMID 38643145, 2024). "In T-ALL patients, TIM3 is upregulated in the peripheral blood and linked to poor outcomes, but we found that most T-ALL patients had low HAVCR2 expression in tumor tissues." (PMID 39080376, 2024). "Collectively, these results indicated that the expression of HAVCR2 correlated with the infiltration of DCs within the tumor microenvironment of CRC." (PMID 38791963, 2024). "In peripheral blood from OS patients, the expression of HAVCR2 is upregulated on CD8+ T‐cells, with higher levels associated with advanced tumour grade and metastasis." (PMID 38568056, 2024). "PD1 (PDCD1), PD-L1 (CD274), CTLA-4, and TIM-3 (HAVCR2) are important immune checkpoints responsible for tumor immune escape." (PMID 36714030, 2023). "A notable correlation was observed between risk score and expression of CTLA4, HAVCR2, PDCD1, PDCD1LG2, and TIGIT, indicating risk scores represent tumor-induced immunosuppression." (PMID 37404760, 2023). "Markers of CTL exhaustion such as HAVCR2 (encoded by the Havcr2 gene) and LAG3 (encoded by the Lag3 gene) increased over this period, suggesting that CTLs had become exhausted inside the tumor." (PMID 37182110, 2023). "Compared with pDCs in PBMCs, tumor-infiltrating pDCs tend to use LGALS9 to affect other cell types by binding HAVCR2." (PMID 37817484, 2023). "HAVCR2 inhibits anti-tumor immunity by interacting with its ligand Galectin 9 (Gal9), phosphatidylserine (Ptdser) high mobility group box 1 (HMGB1), and carcinoembryonic antigen-related cell adhesion molecule 1 (CEACAM1)." (PMID 37005667, 2023). "We validated the upregulation of Il17a, Il17f, Havcr2, and Areg at protein level in Vγ4+ and Vγ6+ cells from the lungs of WT and tumor-bearing KB1P mice by flow cytometry." (PMID 36480166, 2023). "All immune checkpoints were significantly different between the normal and tumor groups (P < 0.05), in which PDCD1, CTLA4, and HAVCR2 were highly expressed in tumor tissues, while CD274, LAG3, and PDCD1LG2 were highly expressed in normal tissues." (PMID 37872211, 2023). "HAVCR2 can affect tumor growth by regulating T-cell activity and infiltration, indicating enhanced immune signal response in PBMCs for whole body immune response." (PMID 38235142, 2023). "A notable association was observed across risk score and the expression of CTLA4, HAVCR2, PDCD1, PDCD1LG2, and TIGIT, indicating risk scores represent tumor-induced immunosuppression." (PMID 37404760, 2023). "Upregulation of TIM-3 was also observed in tumours progressing after anti-PD-1 therapy, and overexpression of HAVCR2/TIM-3 was an indicator of poor prognosis." (PMID 36980527, 2023). "However, the chronic stimulation by tumor antigens and the persistence of the inflammatory stimuli drive these S-associated immune cells to exhaustion, as suggested by the increased expression levels of immune checkpoints including the T-cell receptor HAVCR2 and its specific ligand LGASL9." (PMID 37460925, 2023). "Based on the data downloaded from The Cancer Genome Atlas (TCGA) database and Genotype-Tissue Expression (GTEx), significant overexpression of PDCD1LG2 and for HAVCR2 was noted within tumour tissue." (PMID 36768201, 2023). "HAVCR2 (TIM-3) has been reported to be an important regulatory factor of dendritic cells in anti-tumor immunity." (PMID 36028490, 2022). "This study sheds light on the mechanism of HAVCR2 in tumor immunity and is a promising biomarker for immunotherapy." (PMID 36081997, 2022).
tumor (continued). "COL4A1 expression was also significantly correlated with the expression levels of T cell exhaustion marker genes such as PDCD1, CTLA4, LAG3, and HAVCR2 in all the four tumor types with only two exceptions (CTLA4 in SKCM and LAG3 in STAD)." (PMID 35455650, 2022). "New studies have reported TIM-3, encoded by HAVCR2, as an inhibitory checkpoint protein of tumor-infiltrating T cells." (PMID 36081997, 2022). "Further analysis of the association between the Tumor Recurrence Factor risk score and common immune checkpoints of tumors showed that the Tumor Recurrence Factor risk score was correlated with CD47, CTLA7, HAVCR2, LAG3, PDCD1, and other immune checkpoints." (PMID 35677036, 2022). "HAVCR2 plays an inhibitory role in T cell-mediated immune response, and it is also widely regarded as a negative regulator of anti-tumor immunity, which expected to be an ideal target for the next generation of immunotherapy." (PMID 35444953, 2022). "Immune checkpoint receptor protein TIM3 is a type I membrane protein, also known as hepatitis A virus cell receptor 2 (HAVCR2), which is a negative regulator of anti-tumor immunity." (PMID 36140350, 2022). "PTX3 is closely related to the expression of PD‐1, PD‐L1, CD276, and HAVCR2 in the tumor microenvironment." (PMID 35855654, 2022). "SIGLEC15, PDCD1LG2(PD-L2), TIGIT, PDCD1(PD-1), CD274(PD-L1), CTLA4, LAG3, and HAVCR2(TIM3) are transcripts related to immunological checkpoints that perform vital functions in tumor immune evasion." (PMID 36253777, 2022). "SIGLEC15, PDCD1LG2 (PD-L2), TIGIT, PDCD1 (PD-1), CD274 (PD-L1), CTLA4, LAG3, and HAVCR2 (TIM3) are transcripts related to immunological checkpoints that perform a vital function in tumor immune evasion." (PMID 36042287, 2022). "The Macrophage-Inflamed subgroup, showed infiltration of tumor-associated macrophage (TAM) and increased expression of the immune evasion marker HAVCR2 (TIM-3)." (PMID 36434634, 2022). "IHC staining was performed to examine CD209 and HAVCR2 protein levels in GC tissues and corresponding non-tumor tissues." (PMID 36106123, 2022). "Immune checkpoint receptor protein TIM3 is a type I membrane protein, also known as hepatitis virus cell receptor 2 (HAVCR2), which is a negative regulator of anti-tumor immunity." (PMID 36140350, 2022). "The IHC results showed that the average expression score of CD209 and HAVCR2 was significantly higher in epithelial tissues of GC than in adjacent non-tumor counterparts." (PMID 36106123, 2022). "HAVCR2 expression was closely bound up with tumor purity as there was a strong relation between stromal score, immune score, and ESTIMATE score in all 39 cancers." (PMID 36081997, 2022). "PDCD1, CD274, CTLA4, LAG3, TIGIT, and HAVCR2 are important immune checkpoints responsible for tumor immune escape." (PMID 35252356, 2022). "SIGLEC15, PDCD1LG2(PD-L2), TIGIT, PDCD1(PD-1), CD274(PD-L1), CTLA4, LAG3, and HAVCR2(TIM3) are immunological checkpoints that perform a vital function in tumor immune evasion." (PMID 35840882, 2022). "It has been proven that the expression of HAVCR2 were significantly higher in tumor tissue samples compared with paracarcinoma tissue." (PMID 34733794, 2021). "The univariate and multivariate analysis revealed that CTLA43 (p=0.00444), HAVCR2 (p=0.0019), age (p=0.0038), pTNM stage (p<0.0001), and tumor grade (p=0.00013) were independent factors affecting the prognosis of KIRC patients." (PMID 34336706, 2021). "HAVCR2 is thought to play a dual role, inducing immune tolerance and promoting tumor cell apoptosis." (PMID 34917126, 2021). "We also found LILRB4 expression to be highly correlated with other inhibitory molecules, specifically PDCD1 (PD1) and HAVCR2 (TIM3), in different tumor types." (PMID 33974041, 2021).